MMP1 (matrix metallopeptidase 1)
Diseases named in the same sentence as MMP1 in open-access papers (continued):
Sharing a sentence is not in itself a finding about the gene and the disease.
breast carcinoma (continued). "This study establishes a machine learning-optimized 3-gene prognostic signature (EGR3, RECQL4, MMP1) that bridges prognostic stratification and tumor-immune interplay in breast cancer, offering both clinical and mechanistic advancements." (PMID 41472745, 2025). "To investigate the mechanistic basis of the three-gene prognostic signature (EGR3, RECQL4, MMP1) in breast cancer progression, we performed differential expression analysis followed by GO and KEGG pathway enrichment analyses between the two molecular subtypes." (PMID 41472745, 2025). "To elucidate the functional roles of the three prognostic signature genes (EGR3, RECQL4, and MMP1) in breast cancer pathogenesis, we conducted comprehensive multi-omics analyses across multiple datasets." (PMID 41472745, 2025). "We performed BBB extravasation experiments to determine the role of MMP1 in breast cancer cell extravasation." (PMID 40885703, 2025). "The biological characteristics of MMP1 in various cancers have been recognized 43-45; for instance, downregulation of MMP1 by BMP-6 can inhibit tumor metastasis in breast cancer." (PMID 39629135, 2024). "Expression of MMP-1 was significantly higher in breast cancer tissues, compared to adjacent normal tissues, in both epithelial and stromal parts of the tissue." (PMID 38321552, 2024). "Our current results also showed that PRDX3 can exert its invasive potential, via upregulation of MMP-1 in breast cancer cells." (PMID 38321552, 2024). "miR-101-3p is decreased in BCBM leading to increased expression of COX-2 and stimulation of COX-2/MMP-1 signaling pathway, promoting trans-endothelial migration of breast cancer cells and extravasation across the BBB." (PMID 39175471, 2024). "In stable YBX1 knockdown breast cancer cells, there was a substantial decrease in both mRNA and protein levels of matrix metalloproteinase-1 (MMP-1) and beta-catenin." (PMID 38255791, 2024). "MMP-1 has previously been reported to promote trans-endothelial migration of breast cancer cells by degrading endothelial junctions in BMECs and permeabilizing the endothelial barrier." (PMID 39175471, 2024). "Knockdown of MMP-1 expression in TNBC cells inhibits breast cancer growth and brain metastasis in a xenograft model." (PMID 39697341, 2024). "Downregulation of MMP1 in tamoxifen-resistant breast cancer cells induces tamoxifen sensitivity in vitro and retards tumor growth in vivo." (PMID 39697341, 2024). "In the present research, the chemotherapeutic activity of TMZ on DMBA persuaded the breast cancer due to the modulation of EGFR/ERK/MMP-1 signaling way in rat model was exhibited." (PMID 38808816, 2024). "Hsa-miR-125b-5p regulates cancer cell growth and proliferation by suppressing the TRAF6/MAPK/NF-κB pathway in osteoarthritic chondrocytes and targeting MMP1 in breast cancer." (PMID 39684278, 2024). "To validate our results in the clinical setting, we analyzed the expression of PRDX3 and MMP-1 in 152 paired breast cancer patient samples." (PMID 38321552, 2024). "In this study, we observed that PRDX3 contributed to the invasive ability in two breast cancer cell lines, via upregulation of MMP-1, which is due to the activation of ERK/AP1 signaling, as demonstrated by multi-pathway reporter array and western blotting." (PMID 38321552, 2024). "Expression of the POU class 1 homeobox 1 transcription factor (Pit-1) in breast cancer patients was positively correlated with the presence of both MMP1 and MMP13." (PMID 36677584, 2023). "Research findings suggest that MMP-1 encourages the proliferation and invasion of breast cancer cells by cleaving the same Arg-Ser bond as thrombin do." (PMID 37513440, 2023). "The expression of MMP1 between breast cancer tissues and normal tissues was significantly different." (PMID 36900408, 2023). "Fibronectin binding to integrin β heterodimeric receptors stimulates the production of MMP1, inducing an MMP1-dependent invasive phenotype in breast cancer cells." (PMID 37772773, 2023).
breast carcinoma (continued). "The results of pathway analysis in ductal type recurrence breast cancer in this study showed a significant influence between vimentin expression and MMP1 expression (p=0.000) and had a strong correlation between the two (β=0.611)." (PMID 38046195, 2023). "The upregulation of a set of MMPs, including MMP1, MMP2, and MMP9, has been associated with worse prognosis in different malignancies including breast cancer." (PMID 38017545, 2023). "Downregulating miR-202-3p enhanced the transmigration ability of breast cancer cells across the BE by mediating the expression of MMP1, which in turn degraded inter-endothelial protein junctions, ZO-1, claudin-5 and β-catenin." (PMID 37190188, 2023). "MMP1 has been described in various advanced cancers and correlated with poor survival of patients as shown in breast cancer and colorectal cancer." (PMID 36677584, 2023). "In comparison to primary breast cancer, miRNA-202-3p, which directly targets MMP-1, is downregulated in brain metastases." (PMID 37818447, 2023). "Here, the methylation array data and bisulfite-PCR assay revealed a single CpG at the promoter, highlighting a significant correlation between its methylation and MMP1 expression levels in tamR and tamS breast cancer cells and tumor tissues." (PMID 35267540, 2022). "We aimed to evaluate the contribution and association of single-nucleotide polymorphisms (SNPs) in MMP genes (MMP1, MMP2, MMP3, MMP7, MMP8, MMP9) with clinicopathological breast-cancer features." (PMID 36009438, 2022). "Recently, the matrix metalloproteinase-1 (MMP1)-rich niche of breast cancer brain metastases (BCBMs) was exploited in the design of NPs that can escape abluminal LRP-1-mediated clearance." (PMID 35215625, 2022). "Elevated MMP-1 activity has been reported to contribute to poor prognosis outcomes in breast cancers." (PMID 35586209, 2022). "The study further revealed that MMP-1 expression was upregulated by hypomethylation in both tamoxifen-resistant breast cancer tissues and MCF-7 cells." (PMID 35586209, 2022). "In the breast cancer xenograft model, reduction of MMP-1 expression significantly inhibited breast cancer growth, brain metastasis, and lung metastasis through reducing TGFa release and phosphor-EGFR expression." (PMID 35037689, 2022). "MMP1 is an oncogene involved in various cancers including breast cancer; however, its role in chemotherapeutic drug resistance remains undetermined." (PMID 35267540, 2022). "MMP-1 expression was found to be increased in the tumor microenvironment in an aging model of breast cancer." (PMID 36291773, 2022). "Macrophage TNF and TGFβ1 present within co-cultures have also been shown to increase the migration of MDA-231 breast cancer cells in a 3D culture model through MMP1 and MT1-MMP, respectively." (PMID 35359423, 2022). "It’s noteworthy that MMP1 upregulation by promoter hypomethylation has been reported with enhanced tamoxifen resistance in breast cancer." (PMID 36483054, 2022). "For example, MMP-1 derived from fibroblasts was found to promote the growth and invasion of breast cancer cells by activating protease-activated receptor 1 (PAR1)." (PMID 36741729, 2022). "Compared to normal breast epithelium, triple negative breast cancer cells and tissues revealed higher level of MMP1 expression, which also showed perfect positive correlation with poor prognosis in breast cancer patients." (PMID 36483054, 2022). "Simultaneously, the expression of MMP1 was significantly upregulated in SUM-149 breast cancer cells with RUNX2 overexpression." (PMID 36483054, 2022). "Consistent with the significant association of their high expression in tumor cells or stromal cells with poor clinical outcomes, MMP-1, -2, -7, -13, and -14 exhibited pro-tumorigenic functions in breast cancer." (PMID 36741729, 2022). "In the stromal microenvironment, SASPs, such as IL-6, IL-8, and MMP-1, can stimulate the proliferation and metastasis of breast cancer cells." (PMID 36291773, 2022).
breast carcinoma (continued). "In contrast, serum MMP-1 levels were significantly lower in patients with breast cancer than in healthy controls, and low serum MMP-1 levels were associated with shorter survival." (PMID 36741729, 2022). "In breast cancer tissue samples, MMP1, SDC1, CD24, and SPP1 showed higher protein expression compared with that in tumor-adjacent tissues, and their expression was positively correlation with tumor subtype and grade." (PMID 35037689, 2022). "Elucidating downstream molecular events initiated by the upregulation of MMP1 should be the next step to better understand the mechanism by which the gene induces tam resistance in breast cancer." (PMID 35267540, 2022). "MMP-1 was reported to be upregulated in Adriamycin MCF-7 breast cancer cells, along with MMP-2 and MMP-9." (PMID 35586209, 2022). "Knockdown of MMP-1 expression in TNBC cells significantly inhibited breast cancer growth and brain metastasis in a xenograft model, indicating that tumoral MMP-1 promotes tumor growth and formation of brain metastasis in TNBC." (PMID 36741729, 2022). "MMP1 expression levels in breast cancer patients also affected patient prognosis for survival, with shorter survival periods in patients with high MMP1 expression than those in patients with low MMP1 expression." (PMID 35267540, 2022). "For example, elevated levels of MMP-1 are indicative of advanced breast cancer and signifies poor prognosis." (PMID 35586209, 2022). "Following the expression profile of TIMP‐1, the activity of MMP‐1 was significantly lower in spheroids with hASCs and breast cancer cells than in spheroids from other models, while the activity of MMP‐9 was similar among spheroids." (PMID 35600659, 2022). "Further validation of the prognostic value of stromal or tumoral MMP-1, -2, -9, and -13 expression in breast cancer is required." (PMID 36741729, 2022). "The matrix metalloproteinase-1 (MMP1) gene was selected because it ranked high in the hypomethylated gene list; its epigenetic regulation was also validated in tamR breast cancer patients." (PMID 35267540, 2022). "Among FoxO members, FoxO1 plays important roles in cell dissemination and anticancer drug resistance in breast cancer due to its direct regulation of the transcription of the metastatic factors MMP-1 and the drug efflux pump multidrug resistance 1 (MDR1)." (PMID 36077661, 2022). "This study suggests that MMP1 is potentially a target gene to control tamoxifen resistance in breast cancer." (PMID 35267540, 2022). "MMP1 has potential as a prognostic biomarker and therapeutic target in breast cancer, but more in vivo and clinical studies are required." (PMID 35037689, 2022). "MMP-1, differentially regulated in breast cancer tissues and served a role in breast cancer invasion and metastasis." (PMID 35057823, 2022). "MMP1 can be a potential target to suppress tamR to achieve better prognoses of breast cancer patients." (PMID 35267540, 2022). "MMP1 promotes proliferation and drug resistance in many cancers, such as lung cancer, breast cancer, and head and neck cancer." (PMID 35205603, 2022). "The methylation and MMP1 expression levels were found to be negatively correlated in the breast cancer tissues (n = 61; r = −0.35; p < 0.05)." (PMID 35267540, 2022). "We detected the expression of MMP-1 in situ and metastatic tumors of breast cancer xenograft in mice, and we found that MMP-1 decreased by 44.23% and 47.23% in FLNA/KO-1 and FLNA/KO-2 groups, respectively." (PMID 35359350, 2022). "Although the orthotopic injection reproduces a more realistic environment of the breast cancer, the subcutaneous approach adopted in this study was enough to explain the efficacy of MMP1 in stimulating the tumor cell growth and drug resistance." (PMID 35267540, 2022). "For the purpose of further exploring the correlation of MMP1 in breast cancer, we detected the MMP1 expression level in 1098 breast cancer samples and 113 normal breast tissues according to the TCGA datasets." (PMID 36483054, 2022).
breast carcinoma (continued). "Downregulation of MMP1 in tamoxifen-resistant breast cancer cells induced tamoxifen sensitivity in vitro and retarded tumor growth in vivo." (PMID 36741729, 2022). "For example, curcumin’s role in breast cancer was reported to mediate an apoptotic mechanism in the breast cancer cells through the inhibition of NFkB, cyclin D, and MMP-1." (PMID 36365104, 2022). "Further investigation with siRNA-mediated MMP-1 gene silencing in breast cancer cells showed an increase in apoptosis by Adriamycin, suggesting that MMP-1 plays a crucial role in the chemoresistance of breast cancer cells towards Adriamycin treatment." (PMID 35586209, 2022). "There are also studies showing that by inhibiting MMP1, bone metastasis in breast cancer patients can be reduced." (PMID 35069702, 2021). "The conditioned medium derived from ZEB1-overexpressing MDA-MB-231 cells can stimulate osteoclast maturation by upregulating MMP-1 and subsequently promote breast cancer metastasis to bone." (PMID 34109218, 2021). "A set of lung metastasis signature (LMS) genes, including EREG, COX2, and MMP1/2, was identified in breast cancer cells with lung metastasis potential." (PMID 34884633, 2021). "Stromal MMP1 stimulated the aggressive behavior of breast cancer cells through PAR1 to promote tumor progression." (PMID 34753916, 2021). "CAF-secreted MMP-1 cleaves PAR1 present in breast cancer cells and generates Ca2+ signals that promote migration." (PMID 34768796, 2021). "MMP1 overexpression by silencing miR-202-3p promotes breast cancer cells to transmigrate through the brain endothelium." (PMID 34445346, 2021). "Some studies have found that elevated expression of MMP-1 can promote the local growth and formation of brain metastases by breast cancer cell." (PMID 34445715, 2021). "The heat map shows the significant correlations between ERO1 and PERK, EIF2 alpha, VEGFA, SERPINE1, PLAU, TFRC and MMP1 in basal tumors, confirming the strong association of ERO1 with the PERK branch of UPR and angiogenesis in basal breast cancer." (PMID 33531624, 2021). "miR-361-5p inhibits the glycolysis, proliferation, and invasion of breast cancer cells by targeting MMP1." (PMID 34445346, 2021). "In this context, MMP-1 is the only matrix metalloproteinase found to be significantly correlated with breast cancer brain metastasis." (PMID 33002044, 2020). "The results highlight that exogenous modulation of miR-202-3p can attenuate the trans-endothelial migration of metastatic breast cancer cells through reduction of MMP-1 signaling." (PMID 33002044, 2020). "Ectopic restoration of miR-202-3p expression downregulates MMP-1 expression, reduces extravasation of brain metastatic breast cancer cells and preserves the barrier integrity." (PMID 33002044, 2020). "Taken together, our data show that restoration of miR-202-3p levels directly target and reduce MMP-1 levels in the brain metastatic breast cancer cells which preserves the brain endothelium integrity and prevents extravasation of tumor cells." (PMID 33002044, 2020). "Our results show that the exogenous modulation of miR-101-3p attenuates the trans-endothelial migration of metastatic breast cancer cells in vitro through reduction of COX-2/MMP1 signaling." (PMID 32645833, 2020). "In the case of breast cancer, curcumin has been reported to mediate breast cancer cell apoptosis via suppression of NFκB, cyclinD, and MMP-1 expression." (PMID 32560351, 2020). "In accordance with that, previous data from our group indicate that MMP1 overexpression in tumor-infiltrating immune cells is an early event at the microinvasive focus of in situ breast carcinomas." (PMID 33396463, 2020). "One study isolated urine exosomes from patients with breast cancer and 26 healthy females and determined the expression of miRNA-21 and matrix metalloproteinase-1 (MMP-1) in the isolated exosomes by quantitative RT-PCR." (PMID 32992445, 2020).
breast carcinoma (continued). "For instance, MMP-1,−2,−7,−9,−10,−11,−13,−14, and−15 were documented for their contribution to breast cancer proliferation and metastasis." (PMID 33042020, 2020). "Our study identified a critical regulatory role of miR-202-3p in brain metastasis and shed light on miR-202-3p/MMP-1 axis as a novel prognostic and therapeutic target that can be exploited to predict and prevent brain metastasis in breast cancer patients." (PMID 33002044, 2020). "MMP1 is found to be overexpressed in breast cancer cells resistant to Doxorubicin and is involved in the development of multidrug resistance." (PMID 30979003, 2019). "Strikingly, in MDA-MB-231 breast cancer cells, the loss of mdig appeared to favor the open chromatin structure of the genome for metastatic genes CXCL12, CXCR4, MMP-1, and MMP-9, while enhancing the formation of closed chromatin for UPA." (PMID 30254753, 2018). "In particular, interstitial collagenase (MMP-1) has been found to be involved in the invasion of breast carcinoma." (PMID 30026761, 2018). "Although the grafted tumor cells were not identified clearly on the bone surface, the strong expression of breast cancer markers cathepsin D and MMP1 near the bone surface indicate the successful tumorigenesis induced by cocultivation with tumor cells." (PMID 30400633, 2018). "A study using a xenograft model of breast carcinoma cells originally demonstrated a critical role for MMP-1 derived from tumor-infiltrating fibroblasts in the cleavage of PAR-1, which appears to drive cancer cell migration and invasive behavior of the tumor." (PMID 30065181, 2018). "It has been previously reported that in MDA-MB-231 breast cancer cells, Uev1A upregulates MMP1, which is a dominant factor." (PMID 29662619, 2018). "We also demonstrated that, in some breast cancers, tumor-stromal interactions play a critical role and that stromal-derived MMP-1 can drive tumor progression, invasion, and metastasis through the activation of PAR1." (PMID 30065181, 2018). "MED1 mediates induction of cell proliferation and migration and the genes associated with it (JUN, FOS, EGFR, VEGF, MMP1, and ERBB4) in breast cancer, which is abrogated when used together with miR-191-inhibition." (PMID 30087366, 2018). "MLK3 is essential for FRA-1 expression in breast cancer cells and raises MMP-1 and MMP-9 by FRA-1, which is important for breast cancer cell invasion and transendothelial migration." (PMID 29596304, 2018). "Both flavonoids suppressed pro-intravasative trigger factors in MDA-MB231 breast cancer cells, specifically MMP1 expression and CYP1A1 activity." (PMID 29593542, 2018). "Some MMPs, including MMP-1, MMP-7 and MMP-12, have also been reported as markers associated with poor prognosis in breast cancer." (PMID 30237810, 2018). "The interaction information analysis revealed moderate effect between the markers -1607 1G/2G of MMP1, -1171 5A/6A of MMP3 and -1562 C/T of MMP9 genes which were conferring risk towards the progression of the breast cancer." (PMID 28961241, 2017). "In conclusion, our results suggest that MMP1–1607 1G/2G, MMP3–1171 5A/6A and MMP9–1562 C/T gene polymorphisms have strong correlation with breast cancer." (PMID 28961241, 2017). "In breast cancer curcumin inhibits cell proliferation by down-regulating the transcription of nuclear factor kappa B (NF-κB), cyclin D and matrix metalloproteinase-1 (MMP-1)." (PMID 28724427, 2017). "Based on the Oncomine database, we discovered that MMP1 expression was significantly elevated in breast cancer samples compared with normal samples in nine datasets." (PMID 29207651, 2017). "For example, MMP1 upregulation in breast cancer spheroids can lead to paracrine PAR1 activation and disintegration in the lymph endothelial barrier in vitro." (PMID 28334049, 2017). "The relationship between mRNA expression of MMP1 and clinicopathological parameters of breast cancer (from the breast cancer gene-expression miner v4.0)." (PMID 29207651, 2017).